OR6F1 (olfactory receptor family 6 subfamily F member 1)
Description:
Odorant receptor.
Synonyms: OST731; OR1-34; OR1-38
Tractability: Antibody: its Gene Ontology location is reachable by antibodies, with high confidence; UniProt places it where antibodies can reach, with medium confidence; UniProt predicts a signal peptide or a membrane-spanning region.
Gene: Protein-coding gene on chromosome 1 (247,711,436 to 247,716,646, reverse strand). Ensembl gene ENSG00000169214.
Subcellular location: Cell membrane
Pathways (Reactome):
Sensory Perception: Expression and translocation of olfactory receptors; Olfactory Signaling Pathway
Gene Ontology:
Molecular function: olfactory receptor activity; G protein-coupled receptor activity
Biological process: detection of chemical stimulus involved in sensory perception of smell; G protein-coupled receptor signaling pathway
Cellular component: plasma membrane; membrane
Genetic constraint (gnomAD): Missense variants: 334 observed, 384.73 expected, observed/expected ratio (o/e) 0.87, 90% interval 0.79 to 0.95. Synonymous variants: 140 observed, 153.03 expected, observed/expected ratio (o/e) 0.91, 90% interval 0.8 to 1.05.
Homologues: Orthologues: chimpanzee OR6F1 (98% identical), macaque OR6F1 (93% identical), dog OR6F1 (90% identical), rat Or6f1 (83% identical), mouse Or6f1 (83% identical). Paralogues in human: OR6M1 (51% identical), OR6S1 (49% identical), OR6J1 (49% identical), OR6X1 (48% identical), OR6C65 (47% identical), OR6C75 (47% identical), OR6C76 (46% identical), OR6T1 (46% identical), OR6C70 (46% identical), OR6C4 (45% identical), OR6C74 (45% identical), OR6V1 (44% identical), and 6 more.
Diseases named in the same sentence as OR6F1 in open-access papers:
OR6F1 is named in the same sentence as 2 diseases in open-access papers, as found by Europe PMC text mining. Sharing a sentence is not in itself a finding about the gene and the disease. The quoted sentences say what the papers report.
cancer (2 papers, 2022). A tumor composed of atypical neoplastic, often pleomorphic cells that invade other tissues. "Of them, OR4A15 and OR6F1 belong to the olfactory receptor family, which can pair with the molecular secreted from neighboring neurons and is also highly expressed in different cancer tissues." (PMID 36000927, 2022). "In order to verify reliable GRSDMs, 22 specific DNA methylation genes related to prognosis obtained in the training set were verified on 11 sets of GEO data, and 8 of the specific DNA methylation genes (DGRK, F2RL3, GRK5, NECAB2, OR1C1, OR2L13, OR6F1, and PIK3R6) had been verified in pan-cancer." (PMID 35885996, 2022).
OR6F1 also shares sentences with these, for which no sentence is quoted: head and neck cancer (1 paper).